MMP9 (matrix metallopeptidase 9)
Diseases named in the same sentence as MMP9 in open-access papers (continued):
Sharing a sentence is not in itself a finding about the gene and the disease.
tumor (continued). "Furthermore, TAMs secrete metalloproteinases such as MMP9 that play a critical role in tissue remodeling by degrading the ECM, creating space for newly formed blood vessels and metastasizing tumor cells." (PMID 37893098, 2023). "Anti‐tumour effects were assessed by measuring pathologic complete response (pCR), survival analysis, immunohistochemistry for E‐cadherin, VEGF, MMP9, MMP2 and Ki‐67, serum measurement of IFNγ and IL‐4, and gene expression analysis of CD105, VEGFa, VEGFR2 and COX2." (PMID 37581480, 2023). "In addition, TAMs suppress the antitumor response by producing IL-10 and prostaglandin E2 and promote tumor cell invasion and metastasis by producing MMP-2 and MMP-9." (PMID 37046639, 2023). "Several studies have found that MMP-9, COX-2, and VEGF expressions exist in many tumor tissues." (PMID 36831374, 2023). "Given that CHD1, CDH2, MMP2 and MMP9 play an important role in the process of EMT, we hypothesize that CCT8 mediate tumor metastasis through EMT." (PMID 37928427, 2023). "Selenite inhibits tumor cell invasion by inhibiting the expression of MMP-2, MMP-9, and uPA." (PMID 37006921, 2023). "MMP-9 mediates MMRN2 degradation and enhances tumor angiogenesis." (PMID 36906534, 2023). "In FFPE-ESCC tumor samples, wherever there is a strong appearance of MMP9, the CD44 is diminished greatly or nonexistent while appearing highly expressed just nearby." (PMID 36671668, 2023). "We have formerly demonstrated that the increased MMP-9 expression originates from BMSCs and not from tumor cells." (PMID 36674806, 2023). "Since epithelial–mesenchymal transition (EMT) is associated with the migration and invasion of cancer cells, we analyzed the expression of EMT markers, matrix metalloproteinase 9 (MMP9), vascular endothelial growth factor (VEGF), and Snail in tumor specimens using real-time PCR." (PMID 37122692, 2023). "Therefore, we examined the MMP-9 content of small extracellular vesicles (sEVs)—which can cross the BBB and are stable in body fluids—to characterise tumours with different invasion capacity." (PMID 36765669, 2023). "In addition to immunosuppressive effects, MDSCs influence the remodeling of the tumor microenvironment and tumor angiogenesis through inducing the production of VEGF, bFGF, Bv8, and MMP9, thereby promoting tumor progression." (PMID 36923251, 2023). "In summary, the inhibition of MMP9 and RELA might explain the tumor growth reduction and prolonged survival by a combination of reduced matrix degradation, lower invasion and reduced growth factor release (i.e. VEGF)." (PMID 37963919, 2023). "Moreover, tumor‐derived CXCL1 and CXCL8 increased CXCR2, ERK and JNK pathways‐dependent production of VEGFA and MMP9 in neutrophils, which led to lymphangiogenesis." (PMID 36670069, 2023). "Meanwhile, the results of in vitro experiments further showed that LW6 (HIF-1α inhibitor) could effectively inhibit tumor metastasis by inhibiting the expressions of HIF-1α, MMP9, N-cadherin, and Vimentin." (PMID 37239383, 2023). "The critical role of MMP-9 in EMT processing and tumor cell invasion is well documented." (PMID 37520464, 2023). "Later in tumor development, neutrophils promote tumor growth through modification of the extracellular matrix, releasing vascular endothelial growth factor (VEGF) and producing matrix metalloprotease (MMP)-9 to stimulate angiogenesis and, ultimately, tumor progression and local invasion." (PMID 36982144, 2023). "It has been reported that chronic behavioral stress increased tumor angiogenesis and growth in ovarian carcinoma cells by β-AR-mediated activation of the cAMP-PKA signaling pathway with consecutive upregulation of VEGF, MMP2, and MMP9." (PMID 36902129, 2023). "Among the secreted MMPs, MMP-2 and MMP-9 have long been considered to play an important role in cancer invasion and metastasis due to their ability to degrade the ECM and basement membrane barriers required for each step of tumor progression." (PMID 37445754, 2023).
tumor (continued). "We hypothesized that mRNA vaccines targeting MMP9 and IGF2BP2 could induce immune infiltration in the tumor microenvironment of patients with immunologically “suppressive” BIS1 and BIS2 tumors." (PMID 36569935, 2022). "In the invasive tumor group we found two significant positive correlations: first between MMP-1 and MMP-2 expression (rho = 0.306, p = 0.031) and second between TIMP-2 and MMP-9 expression (rho = 0.464, p = 0.001)." (PMID 36551933, 2022). "CMCS-NCTD could also exert anti-metastasis effects by inhibiting tumor angiogenesis and decreasing degradation of extracellular matrix by regulating the levels of VEGF, MMP-9 and TIMP-1 in Lewis lung carcinoma metastasis model." (PMID 36463199, 2022). "VIP/VIPR1 signaling maintained tumor proliferation and invasiveness by upregulating the expression of cyclins and angiogenic factors, including cyclin D1, MMP-2/MMP-9, VEGF, and COX-2, as well as stimulating tumor growth through the activation of PKA/ERK1/2 pathway." (PMID 35864952, 2022). "Betulinic acid inhibited the expression of MMP2, MMP9 and p-STAT3 in 4T1 tumor tissues." (PMID 36615262, 2022). "Mechanistically, the EMT that triggers cellular mobility and subsequent dissemination of tumor cells is activated by matrix metalloproteinases 2 (MMP2), MMP9, transforming growth factor-β1 (TGF-β1), and collagen type I 8-11, which are also beneficial to tumor angiogenesis." (PMID 35371324, 2022). "Unlike common anticancer agents, BB94 is a potent extracellular inhibitor of MMP-1, MMP-2, MMP-3, MMP-7, and MMP-9, and thus, it should be released in the extracellular space rather than in tumor cells." (PMID 35440570, 2022). "In addition to its intracellular activity, legumain can be secreted into the tumor microenvironment (TME) in which it contributes to degrading and remodeling the ECM, either by producing the mature forms of MMP2 and MMP9 or by processing cathepsins." (PMID 35067006, 2022). "Western blot analysis further showed that MG treatment downregulated the expression of vimentin, MMP-2 and MMP-9, and upregulated the expression of E-cadherin and TIMP-2, indicating that MG significantly inhibited the EMT and ECM degradation, and prevented tumor metastasis." (PMID 35770085, 2022). "As a newly discovered MMP-9 inhibitor, GNP has excellent inhibitory effect on migration and invasion, and may have great potential in future anti-tumor therapy." (PMID 35954126, 2022). "MMP-9 and VEGF are thought to be involved in tumor progression and metastasis." (PMID 36142326, 2022). "In tumour samples from patients with melanoma and prostate cancer, the mechanism involves the activation of intrinsic STAT3 in B cells leading to the secretion of angiogenic factors S1PR1, MMP9, HIF1a, VEGF, and their accumulation around micro vessels in the tumour." (PMID 35350071, 2022). "MMP-9 and MMP-2 belong to gelatinase, and they are the pivotal hydrolytic enzymes involved in hydrolyzing type IV collagen, a central constituent of the ECM and promoted tumor metastasis." (PMID 35954126, 2022). "GBM tumours are frequently found to have upregulation of MMP-2 and MMP-9." (PMID 36497413, 2022). "Also, a significant decline in expression of Ki‐67, MMP9, and VEGFR2 biomarkers, as well as vasculogenesis, was evident in immunohistochemically stained tumor sections of anti‐MUC1 nanobody‐treated mice." (PMID 34694686, 2022). "MMPs, especially MMP-9 and MMP-2, can digest the ECM and facilitate the metastasis of tumor cells." (PMID 35954126, 2022). "HBV-mediated macrophage release of matrix metalloproteinase 9 (MMP9) and IL-23 induces the blockade of binding of IFN-α to IFNAR1, which could contribute to tumor progression and angiogenesis." (PMID 36544761, 2022).
tumor (continued). "Additionally, neutrophils promote tumor motility, migration and invasion via the release of neutrophil elastase, cathepsin G, proteinase 3, MMP8 and MMP9." (PMID 35682709, 2022). "Moreover, the expression of MMP2 and MMP9 was reversed when FN1 expression was knocked down in HOXD11-overexpressing cells, which suggested the indispensable role of FN1 in HOXD11-mediated tumor progression." (PMID 36151071, 2022). "Furthermore, CAFs secrete MMP-1, MMP-3, MMP-7, MMP-9, and MMP-13, releasing ECM-bound growth factors such as VEGF supporting tumor angiogenesis." (PMID 35572966, 2022). "Other studies presented an in vitro 3D tumor model of breast cancer from the MDA-MB-231 cell line on a silk fibroin scaffold to evaluate the efficacy of cyclosaplin; studies showed a significant decrease in MMP-9 activity in the tumor." (PMID 36077507, 2022). "In primary tumor tissues, they have previously been shown to support tumor growth, invasion, and angiogenesis possibly due to release of ECM remodeling enzymes such as MMP-8, MMP-9, elastase, and cathepsin G." (PMID 35954395, 2022). "The role in tumorigenesis of LCN2, SLC22A17, and MMP9 genes and their gene isoforms as key players of TME interaction was assessed by performing differential transcriptomic analysis of these targets between TCGA tumor samples and GTEx normal tissues." (PMID 36211450, 2022). "It has been shown that N2 neutrophils contribute to tumor growth by several mechanisms such as increased expression of pro-angiogenic genes (MMP9, VEGF) with absent IFN-β and is acquired by neutrophils following the TGF-β treatment/exposure." (PMID 35784290, 2022). "Growing in such a hostile environment (acidosis, hypoxia), tumor and stromal cells may also overexpress some specific enzymes, including MMP-2, MMP-9, FAP-α, legumain, uPA, and some elastases." (PMID 35845404, 2022). "MMP2 and MMP9 are two of the main members of the MMP family that can downregulate the expression of E-cadherin and regulate the cleavage of E-cadherin to produce extracellular fragments, which are essential for tumor metastasis." (PMID 35770085, 2022). "Here, we show that even though URB447 slightly influences the secretion of MMP-2 and MMP-9 in both tumor models, there is no significant change after 24 h." (PMID 36297277, 2022). "In this context, the LCN2–SLC22A17–MMP9 (lipocalin 2—solute carrier family 22 member 17—matrix metallopeptidase 9) pathway contributes to the establishment and remodeling of TME, which is responsible for the tumor progression." (PMID 36211450, 2022). "Our results show that MMP-2, -7, -9, and -13 are mainly expressed by immune cells and hepatocytes, and no tumor cells were positive for MMP-9 or -13." (PMID 35884455, 2022). "NE and MMP-9 are necessary to cleave and remodel laminin, which activates downstream integrin α3β1 and FAK/MEK/ERK signaling, subsequently allowing dormant tumor cells to reenter the cell cycle, leading to the resumption of aggressive metastatic growth of tumor cells." (PMID 36384979, 2022). "Consequently, metastatic tumor mediators (ki-67, N-cadherin, AFP, and gene expression of cyclin D, TERT, VEGF, and MMP9) as well as functional parameters of metastatic seeds (CSCs) were dramatically downregulated in LC-DF(II) NPs." (PMID 36686682, 2022). "The effect of DCH on tumour growth in tumour-bearing mice was explored in in vivo experiments, and the expression of MMP2 and MMP9 and EMT correlation indexes was measured by immunofluorescence and WB, and the changes in cytoskeletal F-actin and β-tubulin were measured by fluorescence." (PMID 36408277, 2022). "HOTAIR facilitated tumorigenesis and tumor development by regulating multiple molecules (e.g., vascular endothelial growth factor (VEGF) and E-cadherin and matrix metalloproteinase-9 (MMP-9)) that were connected with epithelial-to-mesenchymal transition (EMT), tumor invasion, and metastasis." (PMID 35656022, 2022).
tumor (continued). "MMP9 not only contributes to the degradation of ECM but also to the release of hepatocyte growth factor, VEGF, and enhances tumor cell tolerance to stimulate tumor cell metastasis and angiogenesis." (PMID 36364935, 2022). "MMP-7 and MMP-9 belong to the MMP family and are capable of cleaving extracellular matrix proteins (ECMs), which participate in various tumorigenesis activities such as tumour progression and metastasis." (PMID 35783514, 2022). "MMP-9 secreted by invasive cancer cells can degrade the proteins in the extracellular matrix (ECM), which further destroys the histological barriers to tumor cell invasion, and plays a key role in tumor invasion and metastasis." (PMID 35209071, 2022). "The expression of IGF2BP2 and MMP9 was upregulated in tumor tissues compared with adjacent normal tissues (P<0.05)." (PMID 36569935, 2022). "Therefore, restraining the MMP-9 and MMP-2 expression is an effective strategy for tumor metastasis treatment." (PMID 35954126, 2022). "The expression of the P2X7 receptor can be induced by elevated HIF-1α under hypoxia, and then P2X7 can phosphorylate ERK and AKT signaling pathways and increase the accumulation of NF-κB, which promotes tumor cell EMT by regulating the expression of MMP2 and MMP9." (PMID 36139386, 2022). "Moreover, studies have demonstrated the functional interplay between MMP-9 and vascular endothelial growth factor (VEGF), another EMT inducer, in HCC, favoring tumor angiogenesis." (PMID 35081125, 2022). "Tumour cells and fibroblasts communicate with each other, including autocrine and paracrine factors, including IL-8, resulting in the upregulation of MMP2 and MMP9 degradable extracellular matrix (ECM) components that trigger tumour invasion." (PMID 35941973, 2022). "Finally, we explored MMP9 and IGF2BP2 expression levels in the three subtypes and found that the two potential tumor antigens were lowest in BIS3 and highest in BIS2 (Kruskal-Wallis test, P< 0.001)." (PMID 36569935, 2022). "Interestingly, we observed in tumor samples higher levels of MMP-2 and MMP-9, along with lower levels of MMP-14, their main activator." (PMID 36518899, 2022). "Moreover, in the circBRWD3 overexpression tumor model, E-cadherin was upregulated, while N-cadherin, Vimentin, MMP2, and MMP9 were downregulated." (PMID 36443711, 2022). "Since MMP-9 can also regulate VEGF, this downregulation further affects tumor angiogenesis." (PMID 36686732, 2022). "The literature suggest a link between an increased content of MMP9 protein and negative status of hormonal receptors and a higher tumor grade." (PMID 36293492, 2022). "Moreover, CD147 acts as a key role in mediating tumor cell invasiveness via regulating MMP expression, such as MMP-2 and MMP-9 in adjacent cancer cells or CAFs." (PMID 35464411, 2022). "Thus, inhibiting the MMP-9/TGF-β axis eliminates the immunosuppressive effect of neutrophils and suppresses their tumor-promoting functions." (PMID 36072957, 2022). "Finally, we observe the changes in tumor volume, the expression of inflammation-related genes, and tumor immune cell infiltration in the tumor to explore the synergistic mechanism of HMOX1/MMP9/TNFRSF11B and PD1/PD-L1 in HCC." (PMID 36189226, 2022). "MMP9 results showed a similar pattern to non-metastatic stages (I, II, and III) in tumor tissue heparanase levels, as MMP9 presented a huge increase in tumor tissue compared to non-tumor adjacent tissue, especially in stage II." (PMID 36139645, 2022). "The surface change of O-NP changed from positive to negative upon binding MMP-9 in tumor tissue, which results in the enhanced endocytosis of tumor cells." (PMID 35845404, 2022). "Indeed, tumor cells attenuate the immune anti-tumoral action by MMP-2, MMP-9, MMP-13, and MMP-14 secretion, leading to T-cell activity hindrance." (PMID 35572966, 2022).
tumor (continued). "In the tumour cells, cabozantinib interrupts VEGFR1/VEGFR2/c-KIT/TIE2 pathways, downregulating angiogenic factors (HIF1α, VEGFA) and vascular remodelling factors (MMP2, MMP9)." (PMID 35106125, 2022). "MMP-2 and MMP-9, also known as Gelatinase A and B, respectively, play critical roles in tumor cell invasion and metastasis, as they can degrade the major components of the extracellular matrix (ECM), a major component of the tumor microenvironment." (PMID 36611945, 2022). "Except for tumors without normal tissue data, MMP-9 expression was significantly higher in tumor samples than in normal samples." (PMID 35178444, 2022). "Type-IV collagenase MMP-9 plays an important role in degrading extracellular matrix proteins and can regulate the vascular endothelial growth factor (VEGF), thereby affecting the formation, invasion, and metastasis of tumor blood vessels." (PMID 36686732, 2022). "AITC effectively suppressed protein expressions of MCL-1, MMP-9, VEGF, and XIAP in the tumor area." (PMID 36142326, 2022). "Given the importance of these mechanisms, we investigated whether hsa-miR-30a-3p functions as a tumor-suppressor miRNA through MMP2 and MMP9 suppression in BC." (PMID 35449123, 2022). "Consistent with this hypothesis, it has been shown that the expression of several proangiogenic factors, such as VEGF, MMP2, MMP9 and HIF-1α, which are highly upregulated in IHs during the proliferative phase, decrease after tumor involution." (PMID 35563552, 2022). "Outside of MMP9 inhibition, TIMP-1 may contribute to other tumor-supporting phenomena including enhanced proliferation and epithelial to mesenchymal transition." (PMID 35200382, 2022). "CD44 can promote tumor metastasis, and then, CTSK and MMP-9 were detected, and both were positive." (PMID 36005209, 2022). "To assess whether the combined effects of CXCL12 and CXCL11 on tumor cell invasion involve MMPs as an intermediate, we focused on the gelatinases MMP-2 and MMP-9, which represent known targets of CXCL12 and CXCL11." (PMID 36539774, 2022). "MMP9 and MMP2 accelerate tumor metastasis by invading lymphatic vessels and small vessels." (PMID 35069767, 2022). "Using immunohistochemistry, we showed that MMP9 was expressed by inflammatory cells but not by tumor cells." (PMID 34980260, 2022). "In addition, The epithelial-mesenchymal transition (EMT), which facilitates the tumor cell metastasis and invasion, is triggered by many stimuli, such as matrix metalloproteinases 2 (MMP2), MMP9, and transforming growth factor-β1 (TGF-β1)." (PMID 35371324, 2022). "Furthermore, HPSE is involved in tumor metastasis and angiogenesis by regulating the expression of downstream effector genes such as HGF, MMP-9, and VEGF." (PMID 35204054, 2022). "Furthermore, the alleviation of the immunosuppressive TME decreased the secretion of MMP-9 and VEGF-A in tumors, which in turn inhibited tumor growth and metastasis." (PMID 36311793, 2022). "However, both the MMP-9 and HPSE, whose expression is upregulated in many primary human tumors, including CRC, and plays a primary role in tumor development and metastasis, were moderately expressed also in concentrated Matrigel samples." (PMID 36551219, 2022). "The tumor samples have been stained with CD4, CD8, CD68, and MMP9 immune stain markers." (PMID 35083113, 2022). "MMP-9 was differentially expresses according to the clinical stage and was specifically positively correlated with the tumor stage in ACC, BLCA, and KIRC, in which MMP-9 expression increased with tumor progression." (PMID 35178444, 2022). "Downregulation of MMP9, EGFR, VEGFR and STAT3 in HepG2 cancer cells could appear to play a role in tumor invasion and angiogenesis and to mediate the tumor microenvironment." (PMID 36284117, 2022). "In addition, this subtype promotes the vascularization of tumor cells by releasing VEGF and MMP9, and is also involved in the epithelial-mesenchymal transition (EMT), pushing the invasion of tumor cells into benign tissue." (PMID 36140470, 2022).